TRPA1 (transient receptor potential cation channel subfamily A member 1)
Diseases named in the same sentence as TRPA1 in open-access papers (continued):
Sharing a sentence is not in itself a finding about the gene and the disease.
Alzheimer disease (18 papers, 2017 to 2026). A progressive, neurodegenerative disease characterized by loss of function and death of nerve cells in several areas of the brain leading to loss of cognitive function such as memory and language. "For example, TRPA1‐deficient mice were more likely to sustain damage post ischaemia and TRPA1 channel activation in Alzheimer's disease may have a crucial role in regulating astrocyte‐mediated inflammation." (PMID 32608035, 2020). "Inflammation occurring in many neurodegenerative diseases, such as multiple sclerosis and Alzheimer's disease, leads to changes in the cellular environment that will favor the activation of oligodendrocyte TRPA1." (PMID 36762504, 2023). "Another in vivo study on an Alzheimer’s disease mouse model suggests that TRPA1 mediates in Aβ-induced inflammatory responses of astrocytes and contributes to AD development." (PMID 36533180, 2022). "TRPA1 contributes to the calcium mediated neuronal hyperactivity induced by Aβ oligomers in early phases of Alzheimer’s disease." (PMID 33076385, 2020). "TRPA1 activation leads to increased intracellular calcium level with cellular damage aggravating dementia in a genetic mouse model of Alzheimer’s disease." (PMID 31327098, 2019). "Studies have reported that TRPA1 in these cells plays key roles in cerebrovascular diseases and dementia, such as cerebral ischemia and Alzheimer’s disease (AD); however, the contribution of TRPA1 to pathology is controversial, as it has both protective and destructive effects." (PMID 37478173, 2023). "Furthermore, a specific mechanism involving TRPA1 and Alzheimer’s disease (AD) was demonstrated using APP/PS1 Tg/TRPA1 KO mice." (PMID 37296632, 2023). "TRPA1 may facilitate the synaptic dysfunction triggered by oligomeric amyloid-β peptide, implying its role in Alzheimer’s disease." (PMID 34959735, 2021). "Second, it has been shown that TRPA1 activation may contribute to the pathogenesis of Alzheimer’s disease in rodent models." (PMID 33910636, 2021). "Similar to its involvement in other tissues and organs, cortical TRPA1 may contribute to physiological functions such as signal processing in sensory cortex and motor behaviours or in developing pathologies such as in Alzheimer's disease, brain oedema or oxidative-stress induced neuronal damage." (PMID 28424320, 2017). "The expression of TRPA1 is strongly correlated with dysmenorrhea severity in endometriosis patients, and the activation of TRPA1 may trigger the calcium influx, while EVOO may decrease TRPA1 expression and calcium influx in Alzheimer’s disease." (PMID 33008039, 2020).
dermatitis (18 papers, 2014 to 2025). An inflammatory process affecting the skin. "It has also been reported that TRPA1 is associated with inflammation and puritogen responses in dermatitis." (PMID 31488616, 2019). "TRPA1-deficient mice also diminished SP- and oxazolone-evoked scratching behavior and AD responses, as revealed by a decrease of dermatitis score, including erythema, scaring, excoriation, and swelling." (PMID 28364279, 2017). "IMQ-induced psoriasiform skin inflammation was exacerbated in TRPA1-deficient mice." (PMID 38474002, 2024). "Activation of TRPA1 in these cells releases pro-inflammatory factors that promote skin inflammation and hypersensitivity." (PMID 38474002, 2024). "To assess potential mechanisms of TRPA1 on TDI-induced dermatitis, we assess the ear tissue by imaging mass spec on a matrix-assisted laser desorption ionization instrument (MALDI)." (PMID 36877675, 2023). "In the oxazolone and SADBE (squaric acid dibutyl ester) models of allergic contract dermatitis (ACD), the KO of TRPA1 reduced skin inflammation, skin edema, keratinocyte hyperplasia, and scratching behaviors." (PMID 38139833, 2023). "After the dermatitis was induced, we topically treated mice with either diluent or inhibitors of TRPA1 (cardamonin and its natural source, cardamom seeds)." (PMID 36877675, 2023). "In the DNCB (2,4-dinitro-chlorobenzene) model of AD, TRPA1 antagonism or KO resulted in a lower dermatitis score and fewer scratch bouts." (PMID 38139833, 2023). "Using the IMQ model in wildtype and TRPA1 KO mice, there was a significant reduction in the immune cells, inflammatory cytokines, skin inflammation and skin barrier defects in the TRPA1 KO mice." (PMID 38139833, 2023). "Using cell culture and mouse models, we now demonstrate that TDI induced skin inflammation in mice as well as calcium influx in human neurons; each of these findings were dependent on TRPA1." (PMID 36877675, 2023). "Genetically ablating or blocking TRPA1 pharmacologically alleviated itch in mice with oxazolone- and urushiol- induced dermatitis." (PMID 36613861, 2022). "To conclude, TRPA1 activation and sensitization mediate skin inflammation by increasing the release of inflammatory mediators, although their role in immune cells remains to be clarified." (PMID 28364279, 2017). "Both TDI and xylene induce AD-like dermatitis in mice via TRPA1-dependent mechanisms." (PMID 38637696, 2024). "Indeed, it is intriguing that the expression of TRPA1 can be significantly reduced by the application of certain pharmacological drugs commonly used to treat skin inflammation." (PMID 38474002, 2024). "In oxazolone-induced contact dermatitis models, TRPA1 KO and HC-030031 decreased pro-inflammatory cytokines, T cell infiltration, dermatitis score, and edema, indicating that TRPA1 may play a central role in inflammation and pruritus." (PMID 25640188, 2015). "Given that TRPA1 KO and WT groups had similar degrees of inflammation at day 3, but that TRPA1 KO mice showed substantially less inflammation at day 5 than WT counterparts, TRPA1 has a positive role in the additional skin inflammation that occurs between day 3 and 5 in this model." (PMID 31111624, 2019). "Moreover, it has been reported that gallic acid functions as an antagonist of the transient receptor potential ankyrin 1 (TRPA1) channel, and exerts antinociceptive and antiedematogenic effects in various types of dermatitis models induced by TRPA1 agonist, hydrogen peroxide, or carrageenan." (PMID 28208738, 2017). "To further determine its selectivity, we tested the inhibition rate of fluoxetine on other dermatitis-related TRP channels transiently expressed in HEK293T cells, such as TRPV1, TRPV4, TRPA1, and TRPM8." (PMID 40699677, 2025). "TRPA1, on the other hand, exerts a protective role, and blocking or knocking out TRPA1 enhances the IMQ induced dermatitis." (PMID 35457056, 2022).
dermatitis (continued). "Similarly, another study found impaired scratching response in TRPA1 and HTR7 knockout mice with vitamin D analog induced dermatitis." (PMID 36613861, 2022). "By its localization in neuronal and non-neuronal skin cells, TRPA1 potentiates neurogenic skin inflammation by enhancing cellular responses." (PMID 28364279, 2017). "Moreover, TRPV2 and TRPA1 seem to be involved in insulin secretion, TRPV1 and TRPV2 in heart hypertrophy, TRPV3 in skin disorders, TRPV1 and TRPA1 in airway irritation and cough, and TRPV1, TRPV2 and TRPA1 in cancer." (PMID 28333079, 2017). "There were no baseline differences in the WT versus TRPA1-/- mice, indicating that the TDI-induced dermatitis was TRPA1 dependent." (PMID 36877675, 2023). "Unexpectedly, TRPV1 but not TRPA1 protected against the SADBE-induced skin inflammation, suggesting that chronic skin inflammation and persistent itch in SADBE-induced CHS were mediated by distinct molecular mechanisms." (PMID 30301231, 2018). "Apart from TRPV1 and TRPA1, the levels of both IL-4 and IL-13, and epithelial-driven cytokines IL-25 and TSLP are also strongly correlated with expression of cold-activated TRPM8, a channel that is involved in non-neurogenic skin inflammation." (PMID 34276687, 2021).
Anxiety (17 papers, 2015 to 2025). Intense feelings of nervousness, tension, or panic often arise in response to interpersonal stresses. "Furthermore, in mice, TRPA1 governs models of anxiety and depression which are both strongly associated comorbidities of AD." (PMID 36877675, 2023). "Overall, the CUMS paradigm resulted in a anxiety and depression-like phenotype, and the response to chronic stress seems to be TRPA1-dependent." (PMID 40574094, 2025). "Stress and anxiety can modulate TRPA1 activity, potentially exacerbating symptoms in individuals with TRPA1 dysregulation and contributing to the complex interplay between the gut and brain." (PMID 39022308, 2024). "Functional ablation of the TRPA1 channel in mice improved hippocampal functions, demonstrating by reduced anxiety-like behavior, improved fear-related or spatial learning and memory, novel location recognition and social interactions." (PMID 38915349, 2024). "Another cutaneous channel in this class, TRP Ankyrin 1 (TRPA1) is typically activated by temperatures below 17°C, but also modulates itch, inflammation, as well as murine models of anxiety and depression." (PMID 36877675, 2023). "Studies have revealed the involvement of TRPA1 channel modulation in the pathogenesis or treatment of various NPDs such as Alzheimer’s, depression, anxiety." (PMID 34912298, 2021). "We found that Trpa1−/− mice exhibited normal anxiety behaviors in the open field test and elevated-plus maze test." (PMID 29795268, 2018). "The fact that DMTS had a TRPA1-mediated differential effect on anxiety and depression-like behaviour in animals leads to the proposal that anxiety may be differentially regulated from depression." (PMID 40574094, 2025). "With regard to the role of TRPA1 within the central nervous system in depression and anxiety models, accumulating evidence suggests that TRPA1 channels exert a tonic facilitatory effect on affective behaviour, as the modulation of TRPA1 results in anxiolytic- and antidepressant-like effects in mice." (PMID 40574094, 2025). "Our findings provide novel insight into the mechanism of the ameliorating effect of DMTS on depression and anxiety and suggest that TRPA1 is a promising therapeutic target for mood disorders, which exploits new paths for the prevention and cure of depression under chronic stress." (PMID 40574094, 2025). "In Trpa1 wild-type mice, anxiety and depression-like behaviour under chronic stress were measured." (PMID 40574094, 2025). "Additionally, the influence of psychosomatic factors on TRPA1 activity as well as the impact of stress and anxiety on physiological responses were further investigated." (PMID 39022308, 2024). "In addition, their research was the first to identify the presence of TRPA1 in the EWcp nucleus in mice and in humans, which is known to play an important role in anxiety and mood regulation via its urocortinergic neurons." (PMID 39062944, 2024). "Likewise, TRPA1-/- mice also possess antidepressant-like and anxiolytic phenotypes when tested for immobility and anxiety in a forced swim test and an elevated plus-maze test." (PMID 34912298, 2021). "Increases in the methylation rates of TRPA1 tended to be associated with pain intensity or depression, but not with anxiety, in the present study." (PMID 32080151, 2020). "Both TRPV1- and TRPA1-KO mice showed reduced anxiety-related behaviors." (PMID 26915043, 2016). "We carried out behavioural studies using Trpa1 wild-type (WT) and knockout (KO) mice in a CUMS model to detect anxiety- and depression-like behaviour." (PMID 40574094, 2025). "The treatment increased baseline anxiety levels in the MBT partly via TRPA1, and it seemed to reduce anxiety levels in stressed, anxious animals in a TRPA1-dependent manner as well." (PMID 40574094, 2025). "Notably, TRPA1 antagonism could also inhibit anxiety and depression in mice." (PMID 31885641, 2019). "The lack of TRPA1 also prevented the stress-related increase in anxiety levels in the MBT but not in the OFT." (PMID 40574094, 2025).
Anxiety (continued). "In the present study, we aimed to investigate whether the TRPA1 agonist DMTS modulates stress-related brain processes, such as anxiety or depression." (PMID 40574094, 2025).
chronic obstructive pulmonary disease (17 papers, 2012 to 2025). A chronic and progressive lung disorder characterized by the loss of elasticity of the bronchial tree and the air sacs, destruction of the air sacs wall, thickening of the bronchial wall, and mucous accumulation in the bronchial tree. "TRPA1 has been reported to be associated with a number of inflammatory diseases, such as asthma, chronic obstructive pulmonary disease (COPD), and neurodegenerative disorders (multiple sclerosis, Alzheimer’s and Parkinson’s diseases)." (PMID 37511605, 2023). "TRPA1 was also reported to mediate diesel exhaust exposure-induced hypersensitivity of cardiac arrhythmias." (PMID 39323758, 2024). "In chronic obstructive pulmonary disease characterized by persistent respiratory symptoms, TRPA1 dysfunction may contribute to chronic bronchoconstriction and obstructive airway changes." (PMID 39022308, 2024). "Certain transient receptor potential (TRP) channels including TRPM8 and TRPA1 are widely expressed in the respiratory tract and have been shown to be the receptors of cigarette smoke and particulate matter—the main causative factors of chronic obstructive pulmonary disease (COPD)." (PMID 33567636, 2021). "The regulation of airway inflammation involves TRPA1, and any malfunction in this process may disturb the complicated balance of inflammatory responses, contributing to the onset of chronic obstructive pulmonary disease (COPD)." (PMID 39022308, 2024). "In addition, the lipid peroxidation product 4-hydroxy-2-nonenal (4-HNE), a mediator of oxidative stress and a TRPA1 agonist was found to be upregulated in lungs of patients with chronic obstructive pulmonary disease (COPD), and induced release of IL-8 from U937 cells." (PMID 29467763, 2018).
Obesity (17 papers, 2016 to 2024). Accumulation of substantial excess body fat. "AITC—a potent TRPA1 agonist—increases glucose uptake, improves insulin signaling, and mitochondrial function, and reduces the expression of obesity-induced associated inflammation factors TNF-α, and IL-6." (PMID 36875034, 2023). "These molecules, and TRPA1, have been associated with anti-hyperglycaemic and anti-obesity effects which are further discussed herein." (PMID 35455971, 2022). "Furthermore, the TRPA1 agonist cinnamaldehyde has been associated with reduced visceral body fat in mice, associating also TRPA1 signaling with anti-obesity effects." (PMID 28620299, 2017). "Growing experimental evidence suggests that TRPA1 plays an important role in weight gain, obesity, and insulin secretion." (PMID 36971291, 2023). "The antidiabetic and anti-obesity effects of TRPA1 agonists have been well reported." (PMID 34912298, 2021). "However, the anti-obesity mechanism which TRPA1 and its ligands involved need further exploration." (PMID 34249940, 2021). "Therefore, activation of TRPA1 by its ligands might be a promising approach for human obesity treatment and prevention." (PMID 34249940, 2021). "Interestingly, Capsiate was also shown to activate TRPA1; it could exert its effect via TRPA1 in adipose tissues to prevent obesity could be due to its ability to activate TRPA1." (PMID 30518154, 2018). "Published work suggests that Capsiate exerts an anti-obesity effect, while it is also shown to activate other forms of TRP proteins like TRPA1." (PMID 30518154, 2018). "In addition to non-clinical studies, the beneficial effects of modulating TRPV1, TRPA1 and TRPC5 channels in obesity, T2D, atherosclerosis and MS have been investigated in a range of clinical trials." (PMID 35455971, 2022). "TRPA1, as a BAT function stimulator, would therefore appear to be a good pathway to target obesity." (PMID 26883089, 2016). "On the other hand, monocytes from mothers with obesity (n = 3/time point) exhibited suppression of genes involved in interferon signaling (STAT1, GBP5, PSMB8) and response to reactive oxygen species (STRBP, HEBP2, TRAP1, TRPA1) (p value <0.001) with gestational age." (PMID 34195568, 2021).
psoriasis (17 papers, 2017 to 2026). An autoimmune condition characterized by red, well-delineated plaques with silvery scales that are usually on the extensor surfaces and scalp. "In human psoriatic lesion skin, TRPA1 was upregulated, indicating its potential role in driving the inflammatory process associated with psoriasis." (PMID 38474002, 2024). "Recent evidence supports the role of TRPA1 in psoriasis since the application of imiquimod (IMQ) is associated with the expression of TRPA1 in psoriatic lesions observed after drug application." (PMID 35562920, 2022). "It was originally reported that in a murine model of imiquimod (IMQ)-induced psoriasis-like lesions, topical application of the drug was associated with elevated expression of TRPA1 in affected skin areas." (PMID 33802836, 2021). "Activation of TRPA1 in keratinocytes is implicated in the development of psoriasis, while its activation in immune cells is speculated to have suppressive effects on psoriasis pathogenesis." (PMID 38474002, 2024). "Further investigation is nonetheless required to define the molecular pathways controlling TRPA1 activity in psoriasis and to clarify its contribution to epidermal immune regulation and barrier integrity." (PMID 41597266, 2026). "In inflammatory skin disorders, such as atopic dermatitis and psoriasis, TRPA1 is thought to contribute to pathological processes." (PMID 41597266, 2026). "Recent studies on TRPA1 in psoriasis have shed light on its involvement in the pathogenesis of the disease." (PMID 38474002, 2024). "As shown recently by others and our group, TRPV1 and TRPA1 have previously been shown to also play important roles in pathological skin conditions, such as pruritus, atopic dermatitis and psoriasis." (PMID 35457056, 2022). "The protective role for TRPA1 in psoriasis was strengthened by the observation that a 3-weeks treatment with dry food containing mustard seed (5%) reduced IMQ inflammation in mice." (PMID 33802836, 2021). "Mechanistic studies provided contrasting results on the role of TRPA1 in murine models of psoriasis." (PMID 33802836, 2021). "In psoriasis ROS and RNS play a critical role in its pathology inducing oxidative and nitrosative stress activating TRPA1 channels on sensory nerves innervating the skin, causing the release of SP and CGRP." (PMID 33193423, 2020). "We also found that mRNA expression of TRPA1 was up‐regulated 19‐fold (P < 0.05) in the psoriasis lesions compared with HC by RT‐qPCR." (PMID 31111624, 2019). "Herein, we found that TRPA1 was expressed markedly in neutrophils of MM in epidermis from psoriasis patients." (PMID 31111624, 2019). "The percentage of positive‐stained keratinocytes of TRPA1 was increased in the lesions from the psoriasis patients compared with HC." (PMID 31111624, 2019). "The percentage of positive‐stained cells of TRPA1 was increased in the lesions from the psoriasis patients compared with HC (P < 0.0001)." (PMID 31111624, 2019). "The TRPV1 and TRPA1 channels are at the core of the inflammatory process that occurs in various cutaneous neurogenic disorders that are pruritic diseases, such as psoriasis, AD, and Netherton syndrome." (PMID 28364279, 2017). "More recently, the role of TRPA1 in psoriasis has been explored." (PMID 33802836, 2021). "Pharmacological blockade or genetic deletion of TRPA1 could, in fact, worsen psoriasis dermatitis and nocifensive and itch behavior in mice, thus suggesting a protective role for TRPA1 in psoriasis." (PMID 33802836, 2021). "Collectively, these data suggested that TRPA1 activation or inhibition may simultaneously act in a protective manner in psoriasis, arguably by regulation of the activity of TRPV1." (PMID 33802836, 2021). "In recent years, the role of TRPA1 in psoriasis has been explored." (PMID 33133059, 2020).